RN7SKP26 (RN7SK pseudogene 26)
Gene: Miscellaneous RNA gene on chromosome 18 (45,989,653 to 45,989,945, reverse strand). Ensembl gene ENSG00000222179.
Homologues: Orthologues: chimpanzee 7SK (99% identical), mouse Gm55956 (47% identical), mouse Gm55102 (45% identical). Paralogues in human: RN7SKP87 (74% identical), RN7SKP217 (73% identical), RN7SKP9 (73% identical), RN7SKP151 (73% identical), RN7SKP255 (73% identical), RN7SKP90 (73% identical), 7SK (73% identical), RN7SKP203 (73% identical), RN7SKP243 (73% identical), RN7SKP75 (73% identical), RN7SKP176 (72% identical), RN7SKP189 (72% identical), and 284 more.